RTL6 (retrotransposon Gag like 6)
Synonyms: LDOC1L; MAR6; MART6; dJ1033E15.2; DKFZp761O17121; SIRH3
Tractability: PROTAC: ubiquitination databases record sites on it.
Gene: Protein-coding gene on chromosome 22 (44,492,583 to 44,498,233, reverse strand). Ensembl gene ENSG00000188636.
Subcellular location (Human Protein Atlas): Nuclear speckles; Cytosol
Genetic constraint (gnomAD): Loss-of-function variants: 9 observed, 13.08 expected, observed/expected ratio (o/e) 0.69, 90% interval 0.41 to 1.2. The upper end of that interval is the gene's LOEUF score, 1.2, which puts it in group 5 of 6, group 1 being the genes least tolerant of losing a copy. Missense variants: 291 observed, 346.43 expected, observed/expected ratio (o/e) 0.84, 90% interval 0.76 to 0.93. Synonymous variants: 160 observed, 150.54 expected, observed/expected ratio (o/e) 1.06, 90% interval 0.93 to 1.21.
Homologues: Orthologues: chimpanzee RTL6 (99% identical), macaque RTL6 (98% identical), dog RTL6 (95% identical), pig RTL6 (95% identical), mouse Rtl6 (93% identical), rat Rtl6 (93% identical). Paralogues in human: RTL5 (28% identical), RTL10 (23% identical), PEG10 (18% identical), LDOC1 (17% identical), RTL8A (17% identical), RTL3 (17% identical), RTL8B (17% identical), RTL8C (17% identical), RTL1 (16% identical), RTL4 (6% identical).
Diseases named in the same sentence as RTL6 in open-access papers:
RTL6 is named in the same sentence as 6 diseases in open-access papers, as found by Europe PMC text mining. Sharing a sentence is not in itself a finding about the gene and the disease. The quoted sentences say what the papers report.
gastric cancer (1 paper, 2018). A primary or metastatic malignant neoplasm involving the stomach. "RTL6 is a close derivative of RTL7 which has been recognized for its downregulation in pancreatic and gastric cancers and therefore likely acts as a tumor suppressor." (PMID 29435129, 2018).
viral infection (1 paper, 2022). "In addition, it will be important to evaluate the acute and chronic effects of LPS, dsRNA and non-methylated DNA administration, and/or viral infection in the Rtl5 KO and Rtl6 KO mice using other less invasive methods to assess their biological significance in vivo." (PMID 36162816, 2022).
RTL6 also shares sentences with these, for which no sentence is quoted: bacterial infection (1 paper); colorectal cancer (1); fungal infection (1); tumor (1).